SESN2 (sestrin 2)
Diseases named in the same sentence as SESN2 in open-access papers (continued):
Sharing a sentence is not in itself a finding about the gene and the disease.
Insulin resistance (17 papers, 2014 to 2025). Increased resistance towards insulin, that is, diminished effectiveness of insulin in reducing blood glucose levels. "Loss of Sestrin 2 in mice displayed hyperactivation of mTORC1-S6K signaling in the liver and leads to insulin resistance and glucose intolerance when fed with high fat diet." (PMID 30011848, 2018). "Higher SESN2 levels were associated with lower insulin resistance." (PMID 40433409, 2025). "Sesn2 deficiency exaggerated hyper-nutrition and obesity-associated insulin resistance and hepato-steatosis through chronic activation of mTORC1-p70/S6K signaling, which could be effectively reversed by metformin treatment via activating AMPKα." (PMID 34867324, 2021). "Sesn2 deficiency enhances obesity-induced insulin resistance and the progression of diabetes." (PMID 32010489, 2020). "This suggests a potential link between higher SESN2 levels and increased adiposity and insulin resistance in individuals with diabetes." (PMID 40433409, 2025). "Another study on subjects with diabetes showed that the concentration of SESN2 is increased in patients with metabolic syndrome and is especially related to insulin resistance and a high body fat percentage." (PMID 39037665, 2025). "SESN2 has a beneficial effect on physiological processes, including obesity, insulin resistance, and inflammation." (PMID 37488285, 2023). "This correlation can be explained by the protective effect of SESN2 against insulin resistance formerly described." (PMID 36476132, 2022). "A decrease in the intracellular levels of sestrin 2 can lead many adverse sequelae such as oxidative damage, mitochondrial dysfunction, and insulin resistance." (PMID 32548072, 2020). "Increased Sestrin 2 potentiates AMPK activation and suppresses mTORC1-S6K activity in the liver, alleviating insulin resistance and obesity associated nonalcoholic fatty liver disease (NAFLD) pathologies including steatohepatitis and hepatic fibrosis." (PMID 30011848, 2018). "Conversely, the overexpression or activation of SESN2 has been shown to counteract metabolic dysfunction and protect against diet-induced obesity and insulin resistance by modulating AMP-activated protein kinase (AMPK) and mammalian target of rapamycin (mTOR) pathways." (PMID 40433409, 2025). "In experimental models, lack of SESN2 has been associated with increased progression of diabetes and obesity-induced insulin resistance, highlighting its protective role in metabolic stress conditions." (PMID 40433409, 2025). "In this study, we aimed to determine whether liraglutide could effectively reduce insulin resistance (IR) by regulating Sestrin2 (SESN2) expression in L6 rat skeletal muscle cells by examining its interactions with SESN2, autophagy, and IR." (PMID 37296162, 2023). "Furthermore, the ablation of the Sestrin 2 and 3, especially Sestrin 2, provoked hepatic mTORC1-S6K activation and insulin resistance." (PMID 34946801, 2021). "Sesn2, as the inhibitor of mTORC1, is considered to improve insulin resistance." (PMID 32010489, 2020). "Indeed, Sestrin2 and 3 have a protective effect against obesity-induced metabolic dysfunction and insulin resistance, which is revealed by investigating the liver and adipose tissues of Sesn2/3 double knockout (DKO) mice." (PMID 33425907, 2020). "Of note, SESN2 is induced upon hypernutrition, and the genetic ablation of SESN2 exacerbates obesity-induced mTORC1-S6K activation, glucose intolerance, insulin resistance, and hepatosteatosis in the liver of obese mice, all of which are rescued by AMPK pharmacological activation." (PMID 31205582, 2019). "The observed decrease in SESN2 levels among diabetic subjects in our study aligns with earlier research indicating that SESN2 down-regulation could result in metabolic stress and conditions such as obesity and insulin resistance." (PMID 40433409, 2025).
Insulin resistance (continued). "Therefore, the regulation of Sesn2 activity may provide an alternative approach for the prevention of insulin resistance, obesity, and diabetes." (PMID 32010489, 2020). "In the group combining RES and Pilates, there was a significant increase in sestrin 2 (SESN2) and GPX and a decrease in lipocalin-2 (LCN2), the homeostatic model assessment of insulin resistance (HOMA-IR), and malondialdehyde (MDA)." (PMID 40077707, 2025). "The values of the plasma sestrin 2, TRB3, insulin, fasting plasma glucose, lipid profile, and homeostasis model assessment of insulin resistance (HOMA-IR) were compared in 90 obese women with PCOS (BMI > 30), 90 women with nonobese PCOS (BMI < 30), and 90 control patients (BMI < 30)." (PMID 38813505, 2023). "Moreover, several positive correlations emerged between SESN2 and adiposity/insulin resistance indices in the diabetic cohort, while negative correlations were found in the healthy group." (PMID 40433409, 2025). "Therefore, melatonin-stimulated SESN2 may increase SHP gene expression in WT and diabetic mice, resulting in decreased hepatic gluconeogenesis and subsequently improved insulin resistance." (PMID 37488285, 2023). "Sesn2 ablation exacerbates obesity-induced mTORC1-S6K activation, and moreover, the concomitant ablation of Sesn2 and Sesn3 provokes hepatic mTORC1-S6K activation and insulin resistance even in the absence of nutritional overload and obesity." (PMID 33425907, 2020).
Obesity (16 papers, 2014 to 2025). Accumulation of substantial excess body fat. "Recent studies using Sesn2 and Sesn3 knockout (KO) mice have confirmed the role of Sesns in the suppression of age- and obesity-associated metabolic diseases." (PMID 32010489, 2020). "On the other hand, low levels of sestrin 2 in the obese PCOS group may be considered a risk factor for obesity and metabolic disorders." (PMID 38813505, 2023). "Recently, it was found that SESN2 was upregulated upon hypernutrition and obesity in mouse liver, which was critical for maintaining glucose metabolic homeostasis in hepatocytes, and that deficiency of SESN2 exacerbated obesity-induced hepatosteatosis." (PMID 31867002, 2019). "This study was designed to examine the relationship of these two new biomarkers (sestrin 2 and TRB3) associated with metabolic disorders and obesity in PCOS to shed light on further studies on etiopathogenesis and treatment modalities." (PMID 38813505, 2023). "ROS presence in Sesn2 cardiomyocyte-specific knockout and overexpressed mice with HF diet-induced obesity was evaluated in order to determine the level of oxidative stress occurring in LV tissue." (PMID 36010689, 2022). "Further investigation into the link between the Sesn2/Nrf2 pathway and obesity-related oxidative stress is needed." (PMID 36010689, 2022). "In this study, we aim to gain further understanding of the interconnection between Nrf2 and Sesn2 during obesity-related stress and how this relationship can play a role in cardio-protection." (PMID 36010689, 2022). "This study explores the relationship of Sesn2 and Nrf2 and how their interaction plays a role in obesity-related cardiac dysfunction." (PMID 36010689, 2022). "The overexpression of Sesn2 present in tTa-tet-Sesn2 appears to have provided some cardiac protection from cellular damage and inflammation under HF diet-induced obesity." (PMID 36010689, 2022). "Further studies are required to test the role of miRNAs and sestrin 2 in the pathogenesis of obesity and T2DM and their accompanied inflammation." (PMID 34344352, 2021). "The negative correlations that were found in the present work between serum sestrin 2 levels and the levels of miR-29a and microR-122 reveals the complex nature of the pathogenesis of obesity, T2DM and their accompanied inflammations." (PMID 34344352, 2021). "Sesn2 can diminish ROS accumulation, and activate autophagy, thus suppressing age-related diseases, obesity, diabetes, neurodegenerative diseases, and cancer." (PMID 32010489, 2020). "Knockout of SESN2 exacerbated obesity-induced insulin resistance and diabetic progression, which were associated with impaired glucose homeostasis and reduced insulin sensitivity." (PMID 31867002, 2019). "Over-nutrition and obesity induces hepatic Sestrin 2 expression primarily through activation of ER stress signaling." (PMID 30011848, 2018). "A complex interplay between obesity and diabetes may exist in the diabetic cohort, and the smaller negative correlations are overshadowed by the slight increase in SESN2 levels due to these comorbidities." (PMID 40433409, 2025). "Additionally, liraglutide ameliorated obesity-related non-alcoholic fatty liver disease (NAFLD) by activating SESN2 in HFD mice." (PMID 37296162, 2023). "Cardiomyocyte-specific Sesn2 knockout (cSesn2−/−) and Sesn2 overexpressed (tTa-tet-Sesn2) mice and their wildtype littermates (Sesn2flox/flox and tet-Sesn2, respectively) were assigned to either a normal chow (NC) or a high-fat (HF) diet to induce obesity." (PMID 36010689, 2022). "Overall, this study demonstrates a cardioprotective role of Sesn2 under obesity-related stress." (PMID 36010689, 2022). "Even though much is already known about the relationship between Sesn2 and Nrf2, more knowledge is needed in order to fully understand how these two proteins may play a role in cardio-protection under obesity-related stress conditions." (PMID 36010689, 2022).
Obesity (continued). "Further investigation into the interplay of Sesn2 with obesity and mitochondrial dysfunction could provide more insight into the mechanisms by which Sesn2 may provide cytoprotective properties." (PMID 36010689, 2022). "Further investigation into how Sesn2 and Nrf2 expression changes over time during obesity could provide insight into how these proteins interact over time during obesity-related stress conditions." (PMID 36010689, 2022). "Notably, Sesn2 maintains insulin sensitivity by promoting AMPK activation in the liver, and loss of Sesn2 aggravates hepatosteatosis caused by obesity." (PMID 32010489, 2020). "This study was designed to evaluate the relationship of two new biomarkers [tribbles homolog 3 (TRB3) and sestrin 2 levels], which were previously associated with obesity, with metabolic parameters in obese and nonobese women with polycystic ovary syndrome (PCOS)." (PMID 38813505, 2023). "Therefore, regulating SESN2 activity could be an alternative method to prevent IR, obesity, and diabetes." (PMID 37296162, 2023). "Additional investigation into the levels of pro-inflammatory cells present in the company of Sesn2 deficiency or overexpression may elucidate further understanding into the mechanism in which Sesn2 protects cardiac tissue from fibrotic changes during obesity-induced chronic inflammation." (PMID 36010689, 2022). "While we did not observe a significant correlation between SESN2 and HbA1c, SESN2 levels had a positive correlation with insulin, HOMA-IR, and the majority of the obesity and adipogenicity indices." (PMID 40433409, 2025). "Sestrin 2 inhibits mammalian target of rapamycin (MTORC) and activates the adenosine monophosphate-activated protein kinase (AMPK), the main regulator of energy balance; thus, it has a crucial role in protecting against obesity." (PMID 38813505, 2023). "As a result, sestrin 2 and TRB3 may be suggested as biomarkers that can predict the development of obesity in patients with PCOS." (PMID 38813505, 2023). "While we were able to confirm that Sesn2 does provide protection to cardiac function under obesity-related stress, our results do not indicate any clear pattern for the up- or downregulation of Sesn2 or Nrf2 under these conditions." (PMID 36010689, 2022). "While the Sesn2–Nrf2 signaling pathway is well studied, the effects that these proteins have on obesity-related oxidative stress-induced cardiac dysfunction are not fully understood." (PMID 36010689, 2022). "On contrary to the results of the current work, some previous studies reported significant high serum levels of sestrin 2 in obesity with/without T2DM but still showed significant positive correlations with BMI, serum levels of insulin, and HOMA-IR." (PMID 34344352, 2021). "While there are many studies in the literature examining the relationship between sestrin 2 and TRB3 with various diseases, no study has been found examining its relationship with obesity in women with PCOS." (PMID 38813505, 2023).
hepatocellular carcinoma (15 papers, 2017 to 2025). A malignant tumor that arises from hepatocytes. "For instance, in colorectal, lung, and hepatocellular cancers, SESN2 expression is associated with proliferation, metastasis, and survival." (PMID 40661871, 2025). "During glucose shortage, hepatocellular carcinoma cells regulate HK2 levels by elevating SESN2 expression, enhancing SESN2 cytoplasmic localization, and decreasing HK2 mRNA half-life, ultimately suppressing glycolysis." (PMID 40642070, 2025). "Several studies have revealed that a variety of cancers have downregulated SESN2 expression, including bladder cancer and hepatocellular carcinoma." (PMID 39388305, 2024). "MiR-182-5p expression is up-regulated in hepatocellular carcinoma, and the miRNA has been shown to function as an oncogene by targeting various genes, including SESN2 and TP53INP1, related to cancer." (PMID 29662624, 2018). "In liver diseases including acute liver injury, fatty liver diseases, hepatic fibrosis, and hepatocellular carcinoma (HCC), SESN2 is abnormally expressed and correlated with disease progression." (PMID 36841824, 2023). "More specifically, SESN2 may be a prognostic biomarker for hepatocellular cancer." (PMID 36467613, 2022). "Additionally, SESN2 expression was lower in hepatocellular carcinoma tissues than in non-cancerous tissues, and low SESN2 levels were related to positive lymph node metastasis, advanced tumors, and poor prognosis in hepatocellular carcinoma patients." (PMID 31867002, 2019). "However, the relationship between SESN2 expression and the clinicopathological attributes of hepatocellular carcinoma (HCC) is barely investigated." (PMID 28118855, 2017). "In this study, for the first time, we addressed these questions in an in vitro model of cholestasis using a bile acid-treated human hepatoma HepG2 cell line and in vivo using a bile-duct ligation (BDL) experimental model of cholestasis with Sestrin2 wild-type (Sesn2+/+) and knockout (Sesn2−/−) mice." (PMID 35260799, 2022).
neuroblastoma (14 papers, 2017 to 2025). Neuroblastoma (NB) is the most common solid, extracranial childhood tumor. "SESN2 overexpression suffices to promote autophagy in neuroblastoma cells, while loss of SESN2 expression reduces autophagy induced by LSD1 inhibition." (PMID 28783174, 2017). "LSD1 inhibits mTORC1 activity by upregulating SESN2, ultimately enhancing autophagy in neuroblastoma cells." (PMID 39388305, 2024). "One study showed that upon mitochondrial damage, RBX1 promotes ubiquitylation and degradation of Suppression of Sestrin 2 (SESN2) to trigger the generation of mitochondrial ROS, leading to cell death in neuroblastoma cells." (PMID 33731189, 2021). "It is also reported that LSD1 inhibits autophagy in neuroblastoma by SESN2 (Sestrin2)-dependent pathway." (PMID 34491469, 2021). "Sesn2 (Hi95) was first identified as a gene that was activated by hypoxia in human neuroblastoma cells." (PMID 32010489, 2020). "A novel mechanism of suppression of SESN2 was demonstrated in neuroblastoma cells and is mediated by lysine-specific demethylase LSD1." (PMID 31857853, 2019). "Furthermore, the study found an inverse correlation between LSD1 and SESN2 expression in differentiated neuroblastomas, and reported that high LSD1 and low SESN2 levels were each significantly associated with poorer survival." (PMID 40361504, 2025). "SESN2, known as stress-inducible protein, may function in the regulation of cell growth, survival and autophagy, overexpression of SESN2 can promote autophagy in neuroblastoma cells." (PMID 37582720, 2023). "Additionally, the inhibition of lysine-specific demethylase 1 promoted autophagy through the sestrin 2-mTORC1 signaling pathway in the neuroblastoma cell lines SH-SY5Y, SHEP Tet-21/N, and SK-N-BE." (PMID 34784907, 2021). "Besides HDACIs, the inhibition of the other epigenetic regulators such as histone demethylase LSD1 can promote autophagy through the direct control of SESN2 expression in certain physiopathological conditions, such as during inflammation and in neuroblastoma." (PMID 31546746, 2019). "Furthermore, it is unclear whether sestrin 2 acts as a tumor suppressor or promoter in thyroid cancer, head and neck cancer, neuroblastoma, and nasopharyngeal carcinoma, and verification requires more data." (PMID 34784907, 2021). "Our findings elucidate a mechanism whereby LSD1 controls autophagy in neuroblastoma cells through SESN2 transcription regulation, and we suggest that pharmacological targeting of LSD1 may have effective therapeutic relevance in the control of autophagy in neuroblastoma." (PMID 28783174, 2017). "In the context of neuroblastoma, a study showed that lysine-specific demethylase 1 (LSD1) influences the histone modifications of the SESN2 promoter, thereby repressing its expression." (PMID 40361504, 2025). "In colorectal cancer (CRC) tissues and cell lines, sebaceous gland carcinoma, neuroblastomas, bladder cancer tissues and prostate cancer cells, sestrin 2 was downregulated in comparison with related non-cancerous tissues and cells." (PMID 34784907, 2021). "In neuroblastoma cells, LSD1 represses SESN2 expression, which hampers mTORC1 activity." (PMID 32074399, 2020).